IL18 (interleukin 18)
Diseases named in the same sentence as IL18 in open-access papers (continued):
Sharing a sentence is not in itself a finding about the gene and the disease.
gallbladder cancer (1 paper, 2024). "Together, our findings reveal that PTBP3 modulates exon skipping of IL‐18 to promote immune escape in gallbladder cancer, providing a new perspective for gallbladder cancer immunotherapy by blocking ΔIL‐18 production." (PMID 39116343, 2024). "In addition, we analyzed gallbladder cancer single‐cell sequencing data, and found that, although IL‐18 expression was detected in gallbladder cancer cells, there was no way of distinguishing between expression of cIL‐18 or ΔIL‐18." (PMID 39116343, 2024). "In conclusion, our results show that PTBP3 promotes exon skipping of IL‐18 in gallbladder cancer." (PMID 39116343, 2024). "PTBP3 mediated IL‐18 exon skipping to promote immune escape from gallbladder cancer." (PMID 39116343, 2024). "Moreover, the PSI values of IL‐18 in the 12 gallbladder cancer samples were negatively correlated with the expression level of PTBP3 protein, consistent with the finding that PTBP3 promotes exon skipping of IL‐18." (PMID 39116343, 2024). "PTBP3 did not have a significant effect on the biological behavior of gallbladder cancer cells but facilitated immune escape of tumor cells by promoting exon skipping of IL‐18." (PMID 39116343, 2024).
gallbladder polyp (1 paper, 2024). "Using univariable MR analyses and Bayesian model averaging, we identified MIG, IL-18, and IL-2ra as the top three causes of gastric polyp, MIP1b and IL-6 as the top two protective factors for colonic polyp, and an inverse association between IL-9 and gallbladder polyp." (PMID 39439893, 2024).
gastric polyp (1 paper, 2024). "A similar cause-and-effect connection was noted in interleukin-18 (IL-18) involving gastric polyp (IVW: OR: 0.912, 95%CI: 0.852–0.977, p = 0.008)." (PMID 39439893, 2024). "In both univariable analyses and MR-BMA, we found inverse associations of IL-2ra and IL-18 and a positive association of MIG with gastric polyp." (PMID 39439893, 2024).
Gastrointestinal inflammation (1 paper, 2021). Inflammation of the alimentary part of the gastrointestinal system. "Mevalonate kinase deficiency (MVK) is another autoinflammatory disease, known to also be associated with elevated IL-18 and gastrointestinal inflammation." (PMID 34640385, 2021).
genital herpes (1 paper, 2021). Herpes simplex infection of the genitals, most commonly caused by the herpes simplex-2 virus. "At the moment, there is little information about IL-18 production during genital herpes in humans." (PMID 34047696, 2021). "As previous studies have shown that IL-18 is also dispensable for stimulating IFNγ from adaptive memory immune responses, IL-18, along with type I IFN, may present attractive targets for therapeutics aiming to reduce inflammation during genital herpes." (PMID 34047696, 2021).
gestational diabetes (1 paper, 2025). Carbohydrate intolerance first diagnosed during pregnancy. "Accordingly, IL-6, IL-18, and MCP-1 were selected as inflammatory biomarkers, given their potential alterations during gestational diabetes." (PMID 40062150, 2025). "Serum IL-6 and MCP-1 levels were significantly reduced in the gestational diabetes group compared with the control group, while IL-18 levels were not significantly different." (PMID 40062150, 2025). "Furthermore, women with gestational diabetes were found to have lower levels of IL-6 and MCP-1, but not IL-18." (PMID 40062150, 2025).
giant cell arteritis (1 paper, 2010). "The objective was to investigate the potential implication of the IL18 gene promoter polymorphisms in the susceptibility to giant-cell arteritis (GCA)." (PMID 20331879, 2010).
Giardia infection (1 paper, 2021). "In the present study, we confirmed the involvement of A20-mediated NLRP3 deubiquitination in inflammasome activation, CASP1 and GSDMD cleavage, and IL-1β and IL-18 release during Giardia infection." (PMID 34943932, 2021).
Graves ophthalmopathy (1 paper, 2024). An autoimmune disorder of the EYE, occurring in patients with Graves disease. "They demonstrated that the levels of cytokines IL-1 (interleukin-1) and IL-18 (interleukin 18), caspase-3, complement C4A and APOA-IV (apolipoprotein A-IV) were higher in tear exosomes of patients with Graves’ ophthalmopathy, compared to those without ophthalmopathy and healthy subjects." (PMID 39337483, 2024).
Heart block (1 paper, 2024). Impaired conduction of cardiac impulse occurring anywhere along the conduction pathway. "Our data suggests a potential role for IL-18 in IL-6 trans-signaling-linked pathological ion channel remodeling, action potential phenotypes, and increased propensity for heart block." (PMID 39063055, 2024).
hemophilia (1 paper, 2025). Hemophilia is a genetic disorder characterized by spontaneous hemorrhage or prolonged bleeding due to factor VIII or IX deficiency. "In hemophilia and other chronic inflammatory conditions, IL-18 enhances Th1-type immunity, promotes interferon-γ and TNF-α production, recruits monocytes, and sensitizes nociceptors—linking inflammation to neuropathic pain." (PMID 41375720, 2025).
Hernia (1 paper, 2023). "Overall, these results seem to indicate a possible mechanism for macrophage-induced hernia regression via macrophage activation and phagocytic capacity through IL4, IL17a, IL18, and RANTES and intensified tissue remodeling mediated by LIX." (PMID 37429889, 2023). "Furthermore, a possible mechanism for macrophage-induced hernia regression and tissue repair was unveiled through IL4, IL17a, IL18, LIX, and RANTES increase." (PMID 37429889, 2023).
herpes infections (1 paper, 2022). "Additionally, there can be non-inflammasome sources of IL-1β and IL-18, making it challenging to consistently draw direct links between inflammasome activation and pathological observations associated with IL-18 and IL-1β in herpes infections." (PMID 35038917, 2022).
herpes zoster (1 paper, 2024). A common dermal and neurologic disorder caused by reactivation of the varicella-zoster virus that has remained dormant within dorsal root ganglia, often for decades, after the patient's initial exposure to the virus in the form of varicella (chickenpox). "These include elevated levels of cathepsin D and IL-18, which are associated with reduced risk of herpes zoster, as well as increased risk of postherpetic neuralgia with elevated levels of Ficolin-3 and IL-2 receptor α." (PMID 39253091, 2024). "However, elevation in cathepsin D (OR: 0.6807, 95% CI: 0.4638-0.9991, PIVW: 0.0495) and IL-18 (OR: 0.6845, 95% CI: 0.4715-0.9939, PIVW: 0.0464) was associated with a decreased risk of herpes zoster." (PMID 39253091, 2024).
HIV-associated neurocognitive disorder (1 paper, 2024). HIV-associated neurocognitive disorder (HAND) remains a common complication of HIV infection in the combination antiretroviral therapy (ART) era. "Further, in the SIV-macaque model of HIV-associated CVD and HIV-associated neurocognitive disorder (HAND), plasma IL-18, in addition to galectin-3 and galectin-9, was shown to correlate strongly with monocyte activation and turnover." (PMID 39201388, 2024).
hookworm infection (1 paper, 2022). "In addition, decreased IL-18 and RANTES were detected in women with only hookworm infection compared to uninfected women, whereas IL-21 and SDF-1α were increased." (PMID 36330509, 2022).
hyperplasia (1 paper, 2025). An abnormal increase in the number of cells in an organ or a tissue with consequent enlargement. "Animal model studies have demonstrated that IL-18 is a key mediator driving psoriatic epidermal hyperplasia and sustaining chronic psoriatic inflammation." (PMID 40650209, 2025).
hypersensitivity type 1 (1 paper, 2020). "IL18 induces an increase in the serum concentrations of IgE, IL4, and IL13, which are characteristic cytokines of hypersensitivity type 1." (PMID 33255937, 2020).
hyperthyroidism (1 paper, 2013). Overactivity of the thyroid gland resulting in overproduction of thyroid hormone and increased metabolic rate. "The highest concentrations of IL-6, IL-12, and IL-18 were observed in the subjects with GD, which might suggest a strong stimulation of the immune response; however, the difference in proinflammatory cytokine levels between the patients with hyperthyroidism due to GD and TNG was insignificant." (PMID 24367378, 2013).
Hypervolemia (1 paper, 2020). An increase in the amount of intravascular fluid, particularly in the volume of the circulating blood. "The impression that the NLRP3 inflammasome is not activated by hypervolemia is strengthened by data showing that the mRNA level of IL-18, a cytokine which is also regulated by the NLRP3 complex, is not different in H-HD and N-HD patients (H: 1.3 ± 0.6 vs. H: 1.1 ± 0.4, p = 0.222)." (PMID 32138278, 2020).
hypothyroidism (1 paper, 2023). Abnormally low levels of thyroid hormone. "Treatment with Kp10 suppressed the increase in NLRP3/Nlrp3, IL-1β, Il18, and Gasdermin D/Gsmd caused by hypothyroidism at the maternal-fetal interface." (PMID 37047793, 2023). "Hypothyroidism also increased the placental gene expression of Il18 compared to the control (p < 0.01), while treatment with Kp10 reduced expression in hypothyroid animals, matching the control (p > 0.05)." (PMID 37047793, 2023). "Maternal hypothyroidism increased the gene and protein expressions of NLRP3, Caspase 1, IL-1β, and IL-18 in the deciduae and placentae of rats." (PMID 37047793, 2023).
hypovitaminosis D (1 paper, 2024). "Immune cells, like macrophages that produce pro-inflammatory cytokines such as IL12 and IL18, are involved in both MDD and VDD; it is thus conceivable that alterations in the inflammatory status in hypovitaminosis D precede/trigger the fluctuations in the psychosomatic dimensions of MDD." (PMID 38256187, 2024).
Hypoxemia (1 paper, 2020). An abnormally low level of blood oxygen. "HH group had the strongest IL‐18 fluorescence as compared with Hypoxemia group and Hypercapnia group." (PMID 32666671, 2020). "HH group showed the highest expression levels of IL‐18 in comparison with Hypoxemia group (P < .01) and Hypercapnia group (P < .01)." (PMID 32666671, 2020). "Simple effects analyses found increased protein expression levels of IL‐18 in Hypoxemia group (P < .01), but not in Hypercapnia group (P > .05) compared with Sham group." (PMID 32666671, 2020). "Enhanced IL‐18 immunofluorescence was observed in Hypoxemia group, but not in Hypercapnia group compared with Sham group." (PMID 32666671, 2020).
interstitial cystitis (1 paper, 2020). A rare chronic debilitating urogenital disease characterized by urinary frequency, urgency, and pelvic pain. "The role of IL-18 in BOO has not yet been described in the literature; however, it was chosen for analysis as it takes part in other bladder conditions as bladder pain syndrome/interstitial cystitis." (PMID 33381567, 2020).
intestinal tumor (1 paper, 2021). "A basal level of IL-18 in the colonic mucosa is required to maintain barrier integrity since the complete loss of IL-18 predisposes mice to intestinal epithelial damage, fostering an altered inflammatory environment that potentiates intestinal tumor formation." (PMID 34639191, 2021).
intracranial hypertension (1 paper, 2022). A finding characterized by increased cerebrospinal fluid pressure within the skull. "Another group of experiments on animal models of intracranial hypertension showed that increased ICP was significantly associated with increased levels of cytokines, such as IL-6, IL-18, IL-1α and IL-1β." (PMID 36441671, 2022).
intraductal papillary mucinous neoplasm (1 paper, 2021). "This murine model mechanistically showed NLRP3-regulated IL-18-induced eosinophil accumulation and degranulation, merged pancreatic ducts, pancreatic intraepithelial neoplasia 1 (PanIN1), PanIN2, PanIN3, and intraductal papillary mucinous neoplasm (IPMN)." (PMID 34183442, 2021).
Intussusception (1 paper, 2025). An abnormality of the intestine in which part of the intestine invaginates (telescopes) into another part of the intestine. "In patients with melena, the serum IL‐18 level was higher (p = 0.025), and in patients with intussusception serum levels of TNF‐R1 and IFN‐ɣ were significantly higher compared to patients without intussusception (p = 0.033 and p = 0.033, respectively)." (PMID 40590520, 2025).
iris disease (1 paper, 2008). "Finally, we show that the Gpnmb mediated iris disease does not require elevated IL18 or mature B or T lymphocytes." (PMID 18402690, 2008).
iron deficiency (1 paper, 2020). "Interestingly, IL-6 induces hepcidin, which negatively affects erythropoiesis by inducing iron deficiency, whereas cytokines such as IL-18 and IL-23 (which are produced by monocytes and/or macrophages in addition to other cells) increase IFN-γ production." (PMID 32373101, 2020).
ischemia reperfusion injury (1 paper, 2022). Adverse functional, metabolic, or structural changes in ischemic tissues resulting from the restoration of blood flow to the tissue (reperfusion), including swelling; hemorrhage; necrosis; and damage from free radicals. "Surprisingly, mice lacking IL-18 are protected from AKI caused by ischemia-reperfusion injury." (PMID 36091391, 2022).
keratitis (1 paper, 2022). A corneal disease that is characterized by inflammation of the cornea. "Western blot analysis showed that the protein levels of ASC, cleaved CASP1, N-GSDMD, cleaved IL-1β and cleaved IL-18 were all significantly elevated in C. albicans keratitis." (PMID 35463001, 2022). "Our results indicated that multiple proteins that were associated with inflammasome and pyroptosis (NLRP3, ASC, CAP1, GSDMD, IL-1β and IL-18) were highly expressed in C. albicans keratitis." (PMID 35463001, 2022). "When the NLRP3 inflammasome is activated, a large amount of the proinflammatory cytokines IL-1β and IL-18 are released through GSDMD pores, which may trigger and aggravate corneal inflammation and result in enhanced ocular injury in C. albicans keratitis." (PMID 35463001, 2022). "Interestingly, the increased expression of ASC and IL-18 in C. albicans keratitis was only observed at the protein level but not the mRNA level, which may be attributed to the posttranslational regulation of these genes, but this conclusion needs further confirmation." (PMID 35463001, 2022).
lichen planus (1 paper, 2024). A chronic, recurrent, pruritic inflammatory disorder of unknown etiology that affects the skin and mucus membranes. "IL-18 promotor region -137(G/C) polymorphism might be a factor that increase the risk of development of lichen planus in Egyptian patients and this is unlikely with the variation at -656 (G/T) genotype." (PMID 38918874, 2024). "IL-18 promotor region -137(G/C) polymorphism might be a factor that increase the risk of development of lichen planus in Egyptian patients." (PMID 38918874, 2024).
lipid metabolism disorders (1 paper, 2025). "Network pharmacology analysis identified TNF-α, IL-18, IL-1β and PPAR-γ as major targets of LPQ1 in lipid metabolism disorders." (PMID 40730505, 2025).
liver hemangioma (1 paper, 2025). A hemangioma arising from the liver. "In vivo, an orthotopic liver hemangioma mouse model was established, and RFA was performed to evaluate the levels of IL-1β and IL-18, wet-to-dry lung ratio, and inflammation score." (PMID 41280917, 2025).
Lyme disease (1 paper, 2018). Lyme disease (named after the towns in the USA where the disease was first identified) is a bacterial infection caused by Borrelia burgdorferi. "Lyme disease has been associated with the proinflammatory cytokines Interleukin-6, Interleukin-8, Interleukin-12, Interleukin-18 and interferon-gamma; the chemokines CXCL12, CXCL13 and CCL19 and increased levels of proinflammatory lipoproteins." (PMID 30149626, 2018).
lymphoblastic lymphoma (1 paper, 2014). A lymphoma composed of immature small to medium-sized precursor lymphoid cells (lymphoblasts). "Likewise, the low IL-18 group of patients included 5/6 T-lymphoblastic lymphomas." (PMID 24778454, 2014).
Macrocephaly (1 paper, 2008). Occipitofrontal (head) circumference greater than 97th centile compared to appropriate, age matched, sex-matched normal standards. "This study has shown that irrespective of the underlying aetiology, early indications for HPHC (derived from concurring ventriculomegaly and macrocephaly) are accompanied by pro-inflammatory cytokine activation (IL-18 and IFNγ) with highest IL18 concentrations in post-hemorrhagic HPHC." (PMID 19117508, 2008).
malignant mesothelioma (1 paper, 2025). A malignant neoplasm of the pleura or peritoneum, arising from mesothelial cells. "In the literature, other markers are suggested for the diagnosis of malignant mesothelioma and asbestos exposure, such as specific micro-RNAs and IL-18." (PMID 38806807, 2025).
measles (1 paper, 2023). A highly contagious viral infection caused by the measles virus. "However, MeV-induced innate responses likely influence the adaptive responses to infection that lead to virus clearance and protective immunity as IL-18 and IL-1β influence the CD4 and CD8 T cell differentiation phenotypes that characterize recovery from measles." (PMID 36851476, 2023).
Meniere disease (1 paper, 2025). A disease of the inner ear (labyrinth) that is characterized by fluctuating sensorineural hearing loss; tinnitus; episodic vertigo; and aural fullness. "The main purpose of this study is to explore the relationship between inflammatory corpuscles of NLRP6 and serum levels of inflammatory cytokines IL-1β and IL-18 in patients with Meniere’s disease (MD) to provide a new index basis for clinical diagnosis of MD." (PMID 40837366, 2025).
meningioma (1 paper, 2025). A generally slow growing tumor attached to the dura mater. "Differences in the expression of genes relating to innate immunity (such as NLRP3, IL-18 and IL-1B) between meningioma and VS were identified, with VS having a more immune-rich, inflammatory profile than meningioma overall." (PMID 41437121, 2025).
meningococcal infection (1 paper, 2025). Infections with bacteria of the species neisseria meningitidis. "Despite strain and donor variability, meningococcal infection universally induced cytokines CCL20, CXCL1, CXCL8, CXCL10, and IL-18, with significantly higher CCL20 levels 24 h post-MenW cc11 infection." (PMID 40586572, 2025). "Upon meningococcal infection, we observed a mostly universal induction of CCL20, CXCL1, CXCL8, CXCL10, and IL-18 secretion 24 h post-infection, regardless of the specific meningococcal strain used for infection." (PMID 40586572, 2025).
microcephaly (1 paper, 2021). A congenital or acquired developmental disorder in which the circumference of the head is smaller than normal for the person's age and sex. "Presence of NLRP1, NLRP3, and AIM2 together with elevated IL-1β, IL-18, and IL-33 could be detected in the brain of ZIKV-infected patients with microcephaly." (PMID 33796483, 2021).
minimal change nephrotic syndrome (1 paper, 2015). "It participates in different diseases such as ischemia-reperfusion injury, minimal change nephrotic syndrome or transplant rejection, but above all IL-18 is a mediator and a biomarker of ischemic tissue damage causing AKI." (PMID 26175216, 2015).
monoclonal gammopathy (1 paper, 2013). A condition characterized by the abnormal presence of monoclonal immunoglobulins in the blood or urine. "An elevated level of IL-18 is a prominent feature of Schnitzler syndrome, a rare disorder characterized by chronic urticarial rash and monoclonal gammopathy, along with fever, arthralgia, or bone pain." (PMID 24490166, 2013).